EPB41L3 (erythrocyte membrane protein band 4.1 like 3)
Diseases named in the same sentence as EPB41L3 in open-access papers (continued):
Sharing a sentence is not in itself a finding about the gene and the disease.
tumor (40 papers, 2006 to 2025). "Loss of EPB41L3 is reported in multiple cancer types, and it is originally identified as a tumor suppressor." (PMID 33323539, 2020). "EPB41L3 is a tumour suppressor gene that suppresses metastasis by regulating the proper arrangements of actin stress fibres and increasing cell motility associated with metastatic behaviour." (PMID 38960143, 2024). "EPB41L3 (erythrocyte membrane protein band 4.1-like 3), a cytoskeleton protein–membrane anchor with suspected tumor suppressor properties, showed the greatest fold change, with a mean fold increase of almost 16-fold in Def-Ts." (PMID 36992820, 2023). "It is found in lung cancer cells that miR-233 delivered by PMPs promotes tumor invasion by targeting tumor suppressor EPB41L3." (PMID 35659308, 2022). "For instance, microRNA-223 delivered by platelet-derived MPs from NSCLC patients into tumor cells promote invasion by targeting EPB41L3 inside the tumor cells." (PMID 33791226, 2021). "A loss of EPB41L3, presumably caused by aberrant DNA methylation and/or LOH, is frequently observed in cancer, and EPB41L3 is believed to act as a putative tumor suppressor in some cancers, primarily in NSCLC." (PMID 33323539, 2020). "Hsa-miR-223-3p targets the EPB41L3, a potential tumor suppressor gene, the NFIX gene that regulates both cell proliferation and migration, the SLC2A4/GLUT4 is a glucose transporter and a biomarker for many types of malignant tumors." (PMID 31540229, 2019). "Strong immunoreactivity for EPB41L3 was detected along the cell membrane and in the cytoplasm of the non-tumour tissues." (PMID 28969024, 2017). "EPB41L3 (Erythrocyte Membrane Protein Band 4.1 like 3) is a tumor suppressor gene that inhibits cell proliferation, promotes apoptosis and has been found to be highly methylated in many cancers such as lung, cervix, ovarian and breast." (PMID 28881579, 2017). "The deleted 18p11.21 region contains important tumor inhibitory genes, for example EPB41L3, L3MBTL4, ARHGAP28, PTPRM, and ROCK1 (for complete list of genes in deletion regions)." (PMID 22363777, 2012). "Similarly, EPB41L3, a membrane skeletal protein involved in cell adhesion, has demonstrated tumor-suppressive effects across various cancers, including CRC." (PMID 40001597, 2025). "EPB41L3 is a tumor suppressor involved in apoptosis and cell-cycle regulation." (PMID 39723668, 2025). "Interestingly, EPB41L3 and FAM111B proteins play contrasting roles in tumorigenesis with EPB41L3 acting as a tumour suppressor, while FAM111B functioning as a protooncogene, although recent research has challenged this view." (PMID 40840166, 2025). "We also report increased activity of other apoptosis genes following blast including EPB41L3, or erythrocyte membrane protein band 4.1-like 3, and EPB41L3, a tumor suppressor gene strongly expressed in the brain that promotes apoptotic pathways and inhibits cellular proliferation." (PMID 32174881, 2020). "Furthermore, we observed a significant increase of EPB41L3 mRNA and protein in OS cell lines and tumor tissues." (PMID 33323539, 2020). "EPB41L3 is a tumor suppressor that inhibits cell proliferation, and promotes apoptosis." (PMID 29875348, 2018). "This evidence suggests that EPB41L3 acts as a tumor suppressor in pathogenesis of these tumors." (PMID 28969024, 2017). "In this study, we found that overexpression of LINC00052 could upregulate the EPB41L3 expression and it might serve as a tumor suppressor gene in HCC." (PMID 28969024, 2017). "EPB41L3 encodes band 4.1-like protein 3 (also known as protein 4.1B), which interacts with the synaptic cell adhesion molecule 1 (SynCAM1) to recruit NMDA receptors to synapses, and also acts as tumor suppressor." (PMID 25844147, 2015). "Modulation of post-translational methylation may be an important mechanism through which EPB41L3/DAL1 affects tumor cell growth." (PMID 20698951, 2010).
tumor (continued). "GO term enrichment analysis revealed that EPB41L3 was likely to be involved in cell actin filament binding, extracellular organization, cell proliferation, and cell adhesion which is one of the critical steps in tumor metastasis, indicating its specific role in OS metastasis." (PMID 33323539, 2020). "Of the promoters gaining methylation in our sample, many have already been shown to have tumour suppressor activity, including RORa, FAN1, PRDM1, CYGB, L3MBTL4, EPB41L3, with ZNF471 and ZNF671 being specifically silenced by methylation." (PMID 31357948, 2019). "We then focused on 3 aberrant DNA methylation genes—EPB41L3, GPX3, and COL14A1, with validation analysis using additional ESCC tumor tissues and adjacent normal tissues." (PMID 25050929, 2014). "Cluster 1 was characterized by upregulation of tumor-suppressing genes: HNF1B, CCNDBP1, PATJ, EPB41L3, MARVELD2, PTEN in conjunction with cell-cycle genes – GSPT1, GPR19, EAPP, KIT, CDKL1, and stem cell markers – RBBP5, NANOG, NCSTN, ERG, including quiescent stem cell markers—FOXP1, SMARCA2." (PMID 36348001, 2022). "Furthermore, immunohistochemistry assay revealed that the EPB41L3 protein was differentially expressed between human tumour tissues and their matched non-tumour tissues." (PMID 28969024, 2017). "We used methylation specific PCR (MSP) analysis to study DNA methylation status of EPB41L3, GPX3, and COL14A1 genes in tumor and paired surrounding normal tissue from 42 ESCC patients." (PMID 25050929, 2014).
cancer (30 papers, 2007 to 2025). A tumor composed of atypical neoplastic, often pleomorphic cells that invade other tissues. "Methylation of the host tumor suppressor gene, EPB41L3, has been shown to be associated with the presence of cancer at the anal canal and cervix." (PMID 35619332, 2022). "Our findings firstly implicated entirely different roles of EPB41L3 in OS compared with other cancers." (PMID 33323539, 2020). "Downregulation of EPB41L3 in other carcinomas is caused by allelic loss at 18p11.3 or promoter hypermethylation." (PMID 17280610, 2007). "Loss of EPB41L3 may result in disrupting intercellular adhesion, loss of polarity, increased individual motility, and eventual metastasis of cancer." (PMID 33323539, 2020). "The gene EPB41L3 is hypermethylated (29% hypermethylation) only in tumors, confirming its cancer-specific role." (PMID 34205890, 2021). "Several genes conspicuous in the present study are subject to DNA hypermethylation in other cancers, prominently EPB41L3 and GADD45A." (PMID 17280610, 2007). "Moreover, our previous study showed that the severity degree of precancer lesions was related to EPB41L3, a kind of possible cancer suppressor protein." (PMID 35075362, 2022). "Furthermore, the EPB41L3 gene has been found hypermethylated (29% methylation) only in tumors, confirming its cancer-specific role." (PMID 34205890, 2021). "It is evident from the figure that the majority of ERG-high cancers displayed decreased expression of EPB41L3 and increased expression of EPB41L4B, whereas most of the ERG-low carcinomas had expression levels of the two genes within the range of benign tissues." (PMID 20860828, 2010). "These are noteworthy that CXCL12 and EPB41L3 were verified by the GEPIA in COAD and READ cancer types while SCNN1B and PYY were documented only in COAD cancer type by the GEPIA." (PMID 35333898, 2022). "EPB41L3 mRNA was highly significantly (Mann-Whitney p < 0.001) diminished and EPB41L4B increased (p = 0.002) in these cancer tissues." (PMID 20860828, 2010). "EPB41L1 and EPB41L3 were significantly downregulated and EPB41L4B was upregulated in cancer tissues." (PMID 20860828, 2010). "Average expression of EPB41L3 mRNA was significantly lower in carcinomas with hypermethylation of the gene than in those without (1.79 ± 0.50 vs. 1.33 ± 0.61; p = 0.025)." (PMID 20860828, 2010). "Downregulation of EPB41L3, but not of GADD45A, was associated with promoter hypermethylation, which was detected in 79% of carcinoma samples." (PMID 17280610, 2007). "We compared 5′UTR length between the 85 transcripts with upstream TICs (excluding EPB41L3 and SEPTIN9) with the mRNA sequences of 3615 genes that had no recorded link to cancer." (PMID 36142475, 2022).
infection (1 paper, 2018). The state of being infected such as from the introduction of a foreign agent such as serum, vaccine, antigenic substance or organism. "One possibility is that epigenetic changes, such as EPB41L3 methylation, may occur before hrHPV infection and facilitate the virus genome amplification and genetic instability phase, allowing in some women relatively rapid progression to CIN3." (PMID 29679470, 2018).
EPB41L3 also shares sentences with these, for which no sentence is quoted: colorectal cancer (2 papers); glioma (2); ovarian carcinoma (2); renal clear cell carcinoma (2); /T-cell lymphoma (1); adenocarcinoma (1); Autoimmunity (1); benign tumors (1); brain tumor (1); cardiovascular diseases (1); cervical intraepithelial neoplasia (1); COVID-19 (1); cryptococcosis (1); endothelial dysfunction (1); ependymal tumor (1); esophageal cancer (1); laryngeal squamous cell carcinoma (1); lung (1); lymph node metastasis (1); melanoma (1); metastatic cancer (1); nasopharyngeal carcinoma (1); oligodendroglioma (1); pancreatic adenocarcinoma (1); peripheral neuropathy (1); prostate adenocarcinoma (1); rheumatoid arthritis (1); sarcoma (1); spinal cord ependymoma (1); thyroid disease (1).
A further 1 disease shares a sentence with EPB41L3 in 1 paper.